IL17A (interleukin 17A)
Diseases named in the same sentence as IL17A in open-access papers (continued):
Sharing a sentence is not in itself a finding about the gene and the disease.
asthma (continued). "Considering that Th17-high patients are less sensitive or even unresponsive to ICS and that asthma progression differs from more treatable Th2 types of the disease, developing an effective therapy targeting Th17/IL-17A axis would overcome a major unmet need in severe asthma." (PMID 36140430, 2022). "Therefore, IL-17A comodulated with TGF-β1 is involved in airway remodeling in asthma and is related to neutrophils." (PMID 35626330, 2022). "These multiple implications in the pathogenesis of asthma and the promising findings in preclinical mouse models indicated that neutralization of IL-17A effects could be a novel option to treat severe, neutrophilic, or uncontrolled asthma." (PMID 35883573, 2022). "IL-17A was proved to be involved in airway inflammation and airway remodelling in airway diseases, and its levels positively correlated with the severity of asthma." (PMID 36211987, 2022). "Furthermore, the proportion of IL-17A+ memory Th17 cells is increased in female patients with severe asthma than in male patients, while the proportion of IL-4+ memory T cells is similar in female and male patients with severe asthma." (PMID 35625578, 2022). "In the study on treatment of asthma, it can diminish the expression of IL-4, IL-5, IL-13, IL-17A, IgE, CCL5, and CCL11, inhibit NF-kB- and JNK-mediated inflammatory signaling, and reduce oxidative damage through decreasing the activity of ROS and increasing SOD." (PMID 36588723, 2022). "Another study had found that IL-17A and Th17 cells in the plasma of patients with moderate asthma could be suppressed by inhaled budesonide and formoterol treatment." (PMID 35355985, 2022). "In vitro research showed that methylprednisolone could downregulate IL-17A levels in the supernatants of PBMCs from children with moderate and severe asthma." (PMID 35355985, 2022). "The expression and production of IL-17A and IL-17F is enhanced in patients with asthma." (PMID 35883573, 2022). "Hence, mice with experimental asthma induced by local application of house dust mite extract (HDM) display not only prominent airway neutrophilia but also increased release of IL-17A and infiltration of Th17 cells into the airways." (PMID 35883573, 2022). "TNF-α along with IL-17 family of cytokines, including IL-17A/F, is enhanced in severe asthma." (PMID 36517803, 2022). "We stimulated BEAS-2B cells with IL-4, IL-13 and IL-17A to simulate the asthma microenvironment." (PMID 36575422, 2022). "However, an increased IL-17A signal, which activates neutrophils and macrophages, is the main mechanism of refractory asthma." (PMID 35528611, 2022). "After Pearson correlation analysis, it was revealed that the expression levels of LINC00847 in PBMCs of asthma children were positively correlated with IgE concentration, eosinophil count, IL-4, and IL-17A levels, but negatively correlated with the IFN-γ level of asthma children." (PMID 35356750, 2022). "The biological activity of IL-17A, IL-17F, and the heterodimer IL-17A/F is increased in asthma." (PMID 36517803, 2022). "Indeed, both Th17 lymphocytes and type 3 innate lymphoid cells (ILC3) secrete IL-17A and IL-17F, which are overexpressed in bronchial biopsies of some patients with severe asthma." (PMID 35625801, 2022). "Therefore, as a new strategy to treat steroid-resistant asthma, the potential use of antibodies against IL-17A and its receptor has been investigated." (PMID 35454142, 2022). "The neutrophilic inflammation in severe asthma may be orchestrated by Th17 cells and increased expression of IL-17A and IL-17F is described in airways of patients with severe asthma." (PMID 35295917, 2022). "In severe asthma, although the heterodimer IL-17A/F is known to interplay with other cytokines enhanced in the lungs such as TNF-α, the downstream targets, signaling intermediates and functional outcomes of this interaction remain largely unknown." (PMID 36517803, 2022).
asthma (continued). "IL-17 (also called IL-17A), the main contributor of the pro-inflammatory activity of Th17 cells has been demonstrated to be positively correlated with severity and steroid insensitivity of asthma, whereas the detailed mechanisms remain to be explored." (PMID 35958620, 2022). "In addition to the contribution of ILC2s in asthma, there is also evidence that IL-17A production by “inflammatory” iILC2s (or ILC2-17s) as well as ILC3s promote lung inflammatory responses in asthma models." (PMID 35908044, 2022). "Th17 cells and IL-17A are upregulated in the lungs of patients with asthma, especially individuals with severe asthma, suggesting Th17 cells are involved in the pathogenesis of moderate to severe forms of asthma." (PMID 36032162, 2022). "For example, asthma induced by A. versicolor intratracheally manifested as a strong Th17 cell response along with IL-17A, IL-17F, and IL-22 expression, and co-exposure to the house dust mite and A. versicolor also resulted in a combination of Th2 and Th17 responses." (PMID 33441700, 2021). "IL-17A production contributes to the pathogenesis of asthma." (PMID 34366865, 2021). "Severe forms of asthma have been associated with mixed granulocytes or neutrophilic inflammation accompanied by T helper 17 (TH17) cells and its associated cytokines [IL-17A, IL-6, granulocyte colony stimulating factor (G-CSF), tumour necrosis factor α (TNF-α), and C-X-C motif ligand 8 (CXCL8)]." (PMID 35387053, 2021). "Furthermore, enzyme linked immunosorbent assay (ELISA) displayed that the serum levels of interleukin-17A (IL-17A) were up-regulated in patients with asthma (p < 0.05)." (PMID 33980319, 2021). "It has been concluded that the activation of Th17 cells was one of the pathogenesis of asthma: asthmatic patients expressed elevated mRNA and protein of IL-17A which could be closely related to airway hyperresponsiveness." (PMID 34194525, 2021). "However, there is also some evidence that elevated IL‐17A increases the abundance of MMP‐9, an important tissue remodeling protein in asthma and late‐stage increases in IL‐17A concentration can induce apoptosis of neutrophils and eosinophils." (PMID 33747463, 2021). "In conclusion, high-fat diet could influence gut microbiota balance in obese subjects, increasing IL17A expression, being involved in neutrophilic obesity-related asthma." (PMID 33669035, 2021). "Moreover, neutralization of IL-17A is sufficient to inhibit house dust mite (HDM)-induced asthma in mice." (PMID 33754076, 2021). "On one hand, it has been shown that asthmatic patients more susceptible to viral infections have a deficiency of IFN-γ signaling in their epithelium; on the other hand, severe forms of asthma were associated with higher expression of IFN-γ and IL-17A in the airways." (PMID 35055325, 2021). "And there appears increased IL-17A and IL-17F mRNA expression with increased asthma severity." (PMID 34221020, 2021). "Similarly, 17β-E2 and progesterone together regulate the IL-23R expression partially through let-7f miRNAs and increase the production of IL-17A from Th17 cells in severe asthma." (PMID 35096261, 2021). "IL-17A has been identified as a central player in the pathogenesis of severe asthma exacerbations." (PMID 33717165, 2021). "The promotion of inflammation in asthma by IL-17A and IL-17F has been confirmed." (PMID 34180764, 2021). "Data from animal models also support a link between IL-17A and obese asthma." (PMID 33418879, 2021). "Among the genes, IL17A and ADAM33 have been implicated in the severity of asthma." (PMID 33784348, 2021). "Increased production of IL-17A can occur in both asthma and COPD, and may contribute to COPD pathophysiology." (PMID 33526116, 2020). "The study aimed to evaluate the expression of TSLP, IL-33, and IL-17A in human monocyte derived dendritic cells (moDCs) co-cultured with respiratory epithelium and monocyte derived macrophages (moMφs) in asthma, chronic obstructive pulmonary disease (COPD) and healthy controls." (PMID 32842623, 2020).
asthma (continued). "Inflammation in asthma is mediated by type 2 cells, IL-17A, and IFN-gamma secreting cells." (PMID 32102344, 2020). "IL-17A has been discovered to play an important role in more severe asthma phenotypes." (PMID 33126646, 2020). "Obesity did not influence TSLP and IL-33 mRNA expression in any of the evaluated groups, but BMI might impact the IL-17A mRNA expression in asthma." (PMID 32842623, 2020). "In addition, some studies have shown that DCs play a major role in the pathogenesis of asthma because IL-23, which is a Th17-induction factor, is usually produced by DCs and macrophages, and is sufficient to induce IL-17A production in naïve CD4+ T cells." (PMID 32410846, 2020). "IL-17A has a pro-inflammatory role in several models of inflammation, such as asthma or colitis." (PMID 32161582, 2020). "The 298 unique DEGs from asthma cases in response to IL-13+IL-17A treatment were enriched for “cadherin binding” (adj Pcases = 9.0 × 10−7, Pcontrols = 0.067), while the 2717 unique DEGs from controls were enriched for “enzyme binding” (adj Pcontrols = 8.4 × 10−4, Pcases = 0.11)." (PMID 32690065, 2020). "Thus, the differential transcriptional responses to IL-13 and IL-13+IL-17A in ASMCs from asthma cases and controls were enriched for smooth muscle-specific processes and immune dysregulation, two cardinal features of asthma." (PMID 32690065, 2020). "In addition, further phase II studies are evaluating, in patients with severe type 2-low asthma, the efficacy and safety of the anti-IL-23 antibody risankizumab, as well as of an anti-IL-17A monoclonal antibody." (PMID 33329598, 2020). "As an inflammatory factor secreted by Th17 cells, IL-17A (one of the main members of the IL-17 family) plays a vital role in the occurrence of neutrophilic asthma, and the expression level of IL-17A is positively correlated with the severity of asthma." (PMID 32620122, 2020). "Moreover, DAPP1 expression in the lung was highly positively correlated with a panel of pro-inflammatory cytokines, including several that have been implicated in asthma, such as IL1A, IL7, IL12A, IL17A, IL23A, and IL33." (PMID 31869344, 2019). "Increasing the concentration of rhIL-2 in the presence of dexamethasone maintained elevated levels of IL-10 while reducing the IL-17A response, which may provide new avenues for the development of improved clinical therapies for asthma." (PMID 30598515, 2019). "Moreover, expression of TH17-related cytokines including IL-17A and IL-17F has been demonstrated to be correlated with asthma severity in human airway tissue." (PMID 30736433, 2019). "Taken together, these results reveal that cigarette smoking may have association with an IL-17A-mediated inflammatory response and increased MMP-1 and MMP-9 expression in the nasal mucosa of patients with asthma and CRS." (PMID 31653934, 2019). "Our data suggest that aberrant glucocorticoid-driven IL-17A in SR asthma may be a result of the immune environment in these patients, and, in particular, low, but not absent, levels of IL-2." (PMID 30598515, 2019). "A previous study reported that fibrocytes stimulated with IL-17A in asthma patients released proinflammatory factors that may promote neutrophil recruitment." (PMID 30766447, 2019). "In addition, IL17A promotes inflammation in an asthma murine model, with reduced infiltration of eosinophils in the airways of il17a−/− mice." (PMID 31616423, 2019). "Similarly to the COPD data, Th17 cells and their corresponding cytokines, IL-17A and IL-17F, appeared to contribute to the pathogenesis of primarily severe and steroid-resistant asthma." (PMID 30380761, 2018). "Down-regulation of IL-17A showed a significant correlation with progression of asthma severity." (PMID 30915130, 2018). "Moreover, IL-17A in the peripheral blood or sputum of patients with asthma is correlated with the severity of asthma." (PMID 30622974, 2018).
asthma (continued). "In the absence of epigenetic modifications, the lower level of IL-17A in the population of mild asthma may be because of low longevity of IL-17A mRNA." (PMID 30915130, 2018). "Data showed that while, the normalized expression level of IL-17A underwent a down-regulation in both mild (P=0.332) and severe asthma (P=0.006) affected samples, only in severe asthma the expression was statistically significant in comparison with control group." (PMID 30915130, 2018). "IL-17A belongs to Th17 cytokine family, and plays a key role in severe asthma." (PMID 29784924, 2018). "In addition to the vapor form of PAHs that transfers from blood to tissues and interact with DCs, the particulate form of PAHs also contributes to inflammatory responses and diseases, such as the exacerbation of asthma symptoms with an increased IL-17a level." (PMID 28522830, 2017). "IL-17A may induce epithelial structural changes and smooth muscle contraction; the presence of IL-17A in BALF has been associated with asthma severity in clinical studies." (PMID 28245275, 2017). "Importantly, asthmatics with an overexpression of IL-17A and neutrophilia proved to have the lowest lung function and the worst asthma control when compared to other subsets." (PMID 28199353, 2017). "In addition, the abnormal IL-17A, adipsin and CCL11 levels were significantly associated with adult asthma." (PMID 29138487, 2017). "Elevated plasma IL-17A expression in asthma patients may partly contribute to low adipsin level in this study." (PMID 29138487, 2017). "Thus, the increased IL-17A attribution to PM2.5 exposure in this study plays a vital role in these severe asthma symptoms." (PMID 28199353, 2017). "A very recent study shows that IL-17A/IL-4 dual producing cells are important in asthma and may provide a potential explanation for ICS use decreasing IL-17A+ cells." (PMID 27552197, 2016). "In this scenario, IL-17A in allergic rhinitis and asthma may cover both the innate and the adaptive aspects representing the crucial crosstalk between immune system and structural cells such as fibroblasts and airway epithelial cells." (PMID 27212811, 2016). "Also patients with severe asthma were shown to have higher numbers of IL-17A-positive ILC3-like cells in BAL when compared to healthy subjects or patients with mild asthma." (PMID 27212806, 2016). "Our data revealed that airway inflammatory response in severe asthma group was significantly increased, which was characterized by dominated neutrophils accompanied by markedly elevated IL-17A and IL-6, and these inflammatory metrics were consistent with severe asthma and steroid-resistant asthma." (PMID 26974537, 2016). "On the other hand, ELISA results also demonstrated that expression of IL-4, IL-6, and IL-17a was reduced when compared with asthma induced mice and further confirmed that the inflammation response could be inhibited by Nepeta bracteata Benth." (PMID 27073403, 2016). "IL-17A is a central regulator of neutrophilic inflammation during infection of the airways and there is increasing evidence for its role in chronic lung diseases including asthma, COPD and cystic fibrosis." (PMID 26201093, 2015). "Animal models of asthma have shown that IL-17A and IL-22 can be deleterious or protective." (PMID 25860963, 2015). "There is good evidence that IL-17A expression is increased in asthma and that IL-17A may play a role in steroid-resistant asthma." (PMID 25853810, 2015). "In this regard, a placebo-controlled trial has been recently carried out to evaluate the effects on moderate-to-severe uncontrolled asthma of brodalumab, a human IgG2 anti-IL-17RA monoclonal antibody that blocks the biological activity of both IL-17A and IL-17F." (PMID 25878402, 2015).
asthma (continued). "Under these conditions, CD8-depleted PBMCs from the patients with SR asthma produced significantly increased mean concentrations of both IL-17A and IFN-γ compared with the those seen in the patients with SS asthma, although the mean production of IL-10 and IL-13 did not significantly differ." (PMID 25772594, 2015). "For example, IL-17A producing cells have been shown to play a significant role in allergic rhinitis, allergic contact dermatitis and other immunoinflammatory disorders including psoriatic arthritis, multiple sclerosis and asthma." (PMID 25569210, 2015). "In a mouse model of asthma, IL-17F−/− mice exhibited enhanced Th2 response and eosinophil infiltration, while IL-17A−/− mice showed the opposite, suggesting a suppressive role for IL-17F and a promotional role for IL-17A in the induction of asthma through regulating the Th2 response." (PMID 26682905, 2015). "We have previously shown that IL-17A or Th2 cytokines also enhanced mucin (MUC) 5AC and MUC5B induction in NHBE cells, which causes the over production of mucus in chronic airway disorders such as chronic obstructive pulmonary disease (COPD) and asthma." (PMID 26418032, 2015). "IL-17R which responds to IL-17A or IL-17F increased in asthma." (PMID 26612993, 2015). "Patients with SR asthma produced significantly increased IL-17A and IFN-γ levels compared with those in patients with SS asthma, although it was evident that cells from individual patients might overproduce one or the other of these cytokines." (PMID 25772594, 2015). "Marked elevation of IL-17A was detected in the sputum of severe asthma patients." (PMID 26339131, 2015). "Finally, G-CSF, the neutropoietic cytokine induced by IL-23 via IL-17A, suppresses eosinopoiesis in vivo and ex vivo, in a murine asthma model." (PMID 26199466, 2015). "The expression of IL-17A was also noticed in ozone exacerbated asthma." (PMID 26339131, 2015). "Unfortunately, these patients respond poorly to inhaled corticosteroids, the standard asthma therapy, and emerging data suggest that neutrophilic asthma might result from IL-17A (IL-17) production by steroid-resistant Th17 cells." (PMID 24168764, 2014). "Indeed, in lung tissue sections from asthmatic patients there is an overexpression of IL-17A and IL-17F, whose levels correlate with asthma severity, especially in subjects with neutrophilic, steroid-resistant disease." (PMID 23853765, 2013). "The role of IL-17A and/or Th17 cells in asthma has been extensively studied in mouse models." (PMID 23401702, 2013). "Particularly, epithelial STAT3 was identified as a critical regulator of allergen-induced inflammation and AHR in a murine model of asthma, IL-17A-induced STAT3 activation led to CCL11/eotaxin-1 production in HASM, and PDGF-induced STAT3 mediated the proliferation in HASM cells." (PMID 24499258, 2013). "In addition, it has been demonstrated that Th17 cells and their cytokines such as IL-17A and IL-17F are involved in the pathogenesis of severe asthma." (PMID 23577040, 2013). "IL-17A is overexpressed in the lung during acute neutrophilic inflammation and asthma." (PMID 23573194, 2013). "Although both IL-17A and IL-17F have been shown to play a role in asthma, studies of gene knockout mice have suggested that IL-17F may in fact ameliorate the disease process." (PMID 23462708, 2013). "However, a relationship between IL-17A expression and airflow limitation and sputum neutrophil counts were shown suggesting a potential role for IL-17A in a neutrophilic type of asthma." (PMID 24454477, 2013). "IL-17A and IL-17F, which are proinflammatory cytokines released by Th17 cells and crucially involved in neutrophilic inflammation as well as in airway remodeling, are significantly upregulated in bronchial biopsies obtained from patients with severe asthma." (PMID 23853765, 2013). "The sputum concentrations of IL-17A in COPD were increased compared to patients with asthma." (PMID 23331548, 2013).